CYP1A2 (cytochrome P450 family 1 subfamily A member 2)
Description:
A cytochrome P450 monooxygenase involved in the metabolism of various endogenous substrates, including fatty acids, steroid hormones and vitamins. Mechanistically, uses molecular oxygen inserting one oxygen atom into a substrate, and reducing the second into a water molecule, with two electrons provided by NADPH via cytochrome P450 reductase (NADPH--hemoprotein reductase). Catalyzes the hydroxylation of carbon-hydrogen bonds. Exhibits high catalytic activity for the formation of hydroxyestrogens from estrone (E1) and 17beta-estradiol (E2), namely 2-hydroxy E1 and E2. Metabolizes cholesterol toward 25-hydroxycholesterol, a physiological regulator of cellular cholesterol homeostasis. May act as a major enzyme for all-trans retinoic acid biosynthesis in the liver. Catalyzes two successive oxidative transformation of all-trans retinol to all-trans retinal and then to the active form all-trans retinoic acid. Primarily catalyzes stereoselective epoxidation of the last double bond of polyunsaturated fatty acids (PUFA), displaying a strong preference for the (R,S) stereoisomer. Catalyzes bisallylic hydroxylation and omega-1 hydroxylation of PUFA. May also participate in eicosanoids metabolism by converting hydroperoxide species into oxo metabolites (lipoxygenase-like reaction, NADPH-independent). Plays a role in the oxidative metabolism of xenobiotics. Catalyzes the N-hydroxylation of heterocyclic amines and the O-deethylation of phenacetin. Metabolizes caffeine via N3-demethylation (Probable).
Synonyms: P3-450; CP12; CYPIA2; P450(PA)
Tractability: Small molecule: a structure with a bound ligand is known; a high-quality ligand is known; it belongs to a druggable protein family. Antibody: UniProt places it where antibodies can reach, with medium confidence. PROTAC: its protein half-life has been measured; a small molecule that binds it is known.
Target class: Enzyme; Cytochrome P450; Cytochrome P450 1A2; Cytochrome P450 family 1; Cytochrome P450 family 1A
Chemical probes: METHOXSALEN (high quality), PHENOTHIAZINE
Safety:
Unwanted effects reported when the protein is acted on. In parentheses: how it was acted on, where the effect was seen, and who reports it.
Uroporphyria (activation; source: AOP-Wiki)
dose of paroxetine (source: ClinPGx)
dose of paroxetine and fatigue (source: ClinPGx)
drug toxicity (source: ClinPGx)
fatigue (source: ClinPGx)
insomnia (source: ClinPGx)
metabolism (source: ClinPGx)
metabolism of escitalopram (source: ClinPGx)
metabolism of escitalopram and side effects (source: ClinPGx)
nonfatal myocardial infarction (source: ClinPGx)
nonfatal myocardial infarction with coffee consumption (source: ClinPGx)
opioid use disorder (source: ClinPGx)
QT interval (source: ClinPGx)
seizures (source: ClinPGx)
side effects (source: ClinPGx)
spontaneous abortion (source: ClinPGx)
tardive dyskinesia (source: ClinPGx)
Gene: Protein-coding gene on chromosome 15 (74,748,795 to 74,756,607, forward strand). Ensembl gene ENSG00000140505.
Subcellular location: Endoplasmic reticulum membrane; Microsome membrane
Pathways (Reactome):
Metabolism: Aflatoxin activation and detoxification; Aromatic amines can be N-hydroxylated or N-dealkylated by CYP1A2; Biosynthesis of maresin-like SPMs; Biosynthesis of protectins; Methylation; Synthesis of (16-20)-hydroxyeicosatetraenoic acids (HETE); Synthesis of epoxy (EET) and dihydroxyeicosatrienoic acids (DHET)
Gene Ontology:
Molecular function: caffeine oxidase activity; demethylase activity; enzyme binding; estrogen 16-alpha-hydroxylase activity; estrogen 2-hydroxylase activity; heme binding; monooxygenase activity; oxidoreductase activity; oxidoreductase activity, acting on paired donors, with incorporation or reduction of molecular oxygen, reduced flavin or flavoprotein as one donor, and incorporation of one atom of oxygen; protein binding; electron transfer activity; steroid hydroxylase activity; arachidonate 14,15-epoxygenase activity; fatty acid omega-1 hydroxylase activity; hydroperoxy icosatetraenoate dehydratase activity; iron ion binding; oxidoreductase activity, acting on paired donors, with incorporation or reduction of molecular oxygen
Biological process: alkaloid metabolic process; estrogen metabolic process; monocarboxylic acid metabolic process; monoterpenoid metabolic process; oxidative demethylation; retinol metabolic process; steroid catabolic process; toxin biosynthetic process; xenobiotic catabolic process; xenobiotic metabolic process; aflatoxin metabolic process; epoxygenase P450 pathway; long-chain fatty acid biosynthetic process; methylation; omega-hydroxylase P450 pathway; toxin metabolic process; arachidonate metabolic process; cholesterol metabolic process; hormone metabolic process; olefinic compound metabolic process; primary alcohol metabolic process; steroid metabolic process
Cellular component: intracellular membrane-bounded organelle; endoplasmic reticulum membrane; mitochondrion
Genetic constraint (gnomAD): Loss-of-function variants: 35 observed, 34.25 expected, observed/expected ratio (o/e) 1.02, 90% interval 0.78 to 1.36. The upper end of that interval is the gene's LOEUF score, 1.36, which puts it in group 5 of 6, group 1 being the genes least tolerant of losing a copy. Missense variants: 672 observed, 701.81 expected, observed/expected ratio (o/e) 0.96, 90% interval 0.9 to 1.02. Synonymous variants: 288 observed, 293.57 expected, observed/expected ratio (o/e) 0.98, 90% interval 0.89 to 1.08.
Homologues: Orthologues: chimpanzee CYP1A2 (99% identical), macaque CYP1A2 (93% identical), dog CYP1A2 (82% identical), pig CYP1A2 (81% identical), rabbit CYP1A2 (78% identical), guinea pig CYP1A2 (77% identical), rat Cyp1a2 (75% identical), mouse Cyp1a2 (72% identical), tropical clawed frog cyp1a1 (58% identical), zebrafish cyp1a (54% identical). Paralogues in human: CYP1A1 (72% identical), CYP1B1 (37% identical).
Diseases named in the same sentence as CYP1A2 in open-access papers:
CYP1A2 is named in the same sentence as 190 diseases in open-access papers, as found by Europe PMC text mining. Sharing a sentence is not in itself a finding about the gene and the disease. The quoted sentences say what the papers report.
breast carcinoma (30 papers, 2007 to 2025). "An illustrative human study focused on women with BRCA1 mutations (a high-risk group for breast cancer) found that the protective association between coffee intake and breast cancer incidence depended on CYP1A2 genotype." (PMID 40650030, 2025). "Our current study's results reveal that CYP1A2 SNPs (rs17861162) in breast cancer patients are associated with a 21.7% decrease in the frequency of the CC genotype and a 21.6% and 77.8% increase in the frequency of CG and GG genotypes, respectively." (PMID 38433141, 2024). "The CYP1A2-rs17861162 SNP exhibited a shift from the C allele to the G allele in breast cancer patients, resulting in a 21.7% decrease in CC genotype frequency and a 21.6% and 77.8% increase in CG and GG genotypes, respectively, compared to controls." (PMID 38433141, 2024). "Increased CYP1A2 gene activity has also been linked to a heightened risk of breast cancer development." (PMID 38433141, 2024). "Several studies report an association between CYP1A2 and lung and bladder cancers, while its relationship with breast cancer in different ethnicities needs further investigation." (PMID 38433141, 2024). "CYP1A2 rs2470890 polymorphisms have been studied in breast cancer of northern China, and in depression of Chinese Han, as well as in pharmacogenomics analysis among Chinese." (PMID 32814585, 2020). "In summary, the present study indicated that CYP1A2 rs2470890 was associated with breast cancer prognosis among women in northern China." (PMID 28418906, 2017). "Kaplan–Meier 5 year survival curves and multivariate analysis demonstrated breast cancer patients with the CYP1A2 rs2470890 allele T suffered worse OS compared to wild type allele carriers." (PMID 28418906, 2017). "The findings would promise us a functional profiling of the CYP1A2 gene and understand the biological processes associated with breast cancer formation and progression." (PMID 28418906, 2017). "More importantly, CYP1A2 rs2470890 allele T was significantly correlated with unfavourable prognosis of breast cancer patients." (PMID 28418906, 2017). "The main finding was that CYP1A2 rs762551 was significantly associated with risk of early breast cancer events among AI-treated patients with ER+ tumors, both in the exploratory analysis and in the extended cohort." (PMID 27029552, 2016). "Genetic variants of CYP1A2 have been shown to contribute to the risk of lung and breast cancer by interacting with environmental factors and drug metabolism through regulation of enzyme activity." (PMID 25689428, 2015). "Coffee intake in women with CYP1A2*1F C-allele is associated with both smaller breast size and lower breast cancer risk in BRCA1 carriers." (PMID 24349006, 2013). "CYP1A1 and CYP1A2 genotypes are associated with the generation of catecholestrogens, which have been associated with breast cancer risk." (PMID 19287484, 2009). "As breast volume is associated with breast cancer risk in lean women, our finding is compatible with earlier reports of a protective effect of coffee on breast cancer risk restricted to women with the CYP1A2*1F C-allele." (PMID 18813311, 2008). "Compared to women with the AA genotype, the risk estimates for breast cancer associated with one or two C alleles in the CYP1A2 gene were 0.86 (95% CI = 0.60–1.23) and 0.62 (95% CI = 0.30–1.30), respectively." (PMID 17295924, 2007). "Additional investigations have reported associations between CYP1A2 SNPs and breast cancer." (PMID 38433141, 2024). "Cytochrome P4501A2 (CYP1A2) is a key enzyme in the cause of breast cancer (BC)." (PMID 35335208, 2022). "CYP1A2 rs2470890 was significantly associated with the prognosis of patients with breast cancer and could serve as an independent impact factor of prognosis of breast carcinoma." (PMID 28418906, 2017).
breast carcinoma (continued). "Genetic polymorphisms of CYP1A2 have been identified as leading to interindividual variation in the susceptibility to a series of cancer, such as cholangiocarcinoma, lung, colorectal and breast cancer." (PMID 28418906, 2017). "Although the mechanism behind the finding of the present study is not fully understood, the current study provides new insight into how the CYP1A2 rs762551 combined with the functional AhR Arg554Lys variant is linked to prognosis in AI-treated breast cancer patients." (PMID 27029552, 2016). "In the present study, there was a significant interaction between CYP1A2 rs762551 and CYP19A1 rs4646 with a high risk for breast cancer events, especially within five years, among patients with any C-allele of CYP1A2 rs762551 and C/C-carriers of CYP19A1 rs4646." (PMID 27029552, 2016). "CYP1A2 is able to metabolize some polycyclic aromatic hydrocarbons (PAHs), a procarcinogen, to carcinogenic intermediates, so that higher CYP1A2 activity may influence the risk of lung cancer and breast cancer." (PMID 25061471, 2014). "The current findings are inconsistent with studies conducted in Hawaii that described lower percent densities and estrogen levels in premenopausal carriers of the C allele, as well as a lower breast cancer risk among postmenopausal women with at least one C allele for CYP1A2*1F." (PMID 17295924, 2007). "As a speculation, we propose that one or two C alleles may be protective against breast cancer because the CYP1A2 genotype might influence the amount of adipose tissue in the breast and elsewhere." (PMID 17295924, 2007). "These indicated that CYP1A2 genetic polymorphisms might be associated with enzyme inducibility and enzymatic activity, resulting in metabolic disorders of estrogen/progesterone and thereby contributing to increased susceptibility to breast cancer." (PMID 28418906, 2017). "CYP1A2 rs2470890 alone or in combination with other polymorphisms in the oestrogens metabolism related genes might serve as promising prognostic biomarkers of breast cancer." (PMID 28418906, 2017). "This study explores the role of CYP1A2-rs17861162 and ADSL-rs3788579 SNPs in breast cancer risk among Iranian women." (PMID 38433141, 2024). "Studies investigating the role of ADSL and CYP1A2 SNPs in the development and progression of breast cancer are rather limited." (PMID 38433141, 2024). "Numerous genomic variants, also known as SNPs, including CYP1A2 (rs17861162) and ADSL (rs3788579), appear to be correlated with the risk of breast cancer development." (PMID 38433141, 2024). "Since SNPs are heavily influenced by ethnicity, in this study, we aimed to investigate the role of rs3788579 (ADSL) and rs17861162 (CYP1A2) in female breast cancer patients residing in North-West Iran using PCR–RFLP." (PMID 38433141, 2024). "Previously, CYP1A2 was found to be upregulated by 96-fold in DOX-resistant MCF7 breast cancer cells." (PMID 34799689, 2021). "Alyssin and ITC-2 decrease the activity of enzymes CYP1A1 and CYP1A2 induced by benzo[a]pyrene in MCF-7 breast cancer cells." (PMID 32471217, 2020). "CYP1A1 is particularly implicated in lung, colorectal, breast, and prostate cancers, CYP1B1 in hormone dependent cancers of the prostate, breast, and endometrium, and CYP1A2 in colorectal, lung, and breast cancers." (PMID 29462868, 2018). "In H9c2 cell lines, derived from heart, there was already reported a significant induction of CYP1A2 expression by doxorubicin, as well as in breast cancer MCF7 cell line doxorubicin-resistant." (PMID 28404946, 2017). "The CYP genes with the lowest expression in the TCGA breast cancer cohort were: CYP1A2 (0.010), CYP3A43 (0.029), CYP3A7 (0.033), CYP2C9 (0.044) and CYP3A4 (0.044)." (PMID 28684774, 2017). "Although CYP1A2 is predominantly a hepatic isoform, CYP1A2 protein has been identified in breast cancer tissues." (PMID 29143794, 2017).
breast carcinoma (continued). "This study aimed to analyze the association of genetic polymorphisms in the CYP1A2 and CYP3A4 genes with clinicopathological features, protein expression and prognosis of breast cancer in the northern Chinese population." (PMID 28418906, 2017). "Meanwhile, breast cancer patients carrying the CYP1A2 rs2470890 TT genotype had a poorer OS compared to those with the CC genotype (HR = 3.410, 95% CI 1.535–7.575, P = 0.003)." (PMID 28418906, 2017). "Of the 168 breast cancer specimens immunostain with CYP1A2 protein specific antibody, 117 (69.6 %) were low expression, and 51 (30.4%) were high expression." (PMID 28418906, 2017). "CYP1A2 rs762551 was identified as a new potential predictive marker for early breast cancer events in AI-treated breast cancer patients." (PMID 27029552, 2016). "CYP1A2 is mainly expressed in liver cells but has also been detected in the ER+ breast cancer MCF-7 cell-line after induction." (PMID 27029552, 2016). "After 3 repeated solicitations, only one PI provided us with the full data on CYP1A2 SNPs of breast cancer cases and controls, and by this making total of 71 studies included in our meta-analyses." (PMID 26865042, 2016). "Larger studies with the ability to look at interactions would be useful to elucidate the influence of genetic variation in CYP1A2 and COMT on the risk of developing breast cancer." (PMID 17295924, 2007). "Our observation that the relation between the CYP1A2 genotype and percent density was probably due to an inverse association with the non-dense, i.e., the fatty tissue, may offer a plausible explanation for the discrepancy with the findings on breast cancer risk." (PMID 17295924, 2007). "This cross-sectional analysis examined the relation between mammographic density and the CYP1A2*1F and COMT Val58 Met polymorphisms among 332 breast cancer cases and 254 controls in the Hawaii component of the Multiethnic Cohort." (PMID 17295924, 2007). "Some studies report a negative association between CYP1A2*1F and breast cancer incidence or that the presence of the C allele is protective against the disease." (PMID 38433141, 2024). "While numerous studies have investigated the role of CYP1A2 polymorphisms in breast cancer development among different ethnicities, findings have not consistently aligned." (PMID 38433141, 2024). "Additionally, the interplay between coffee consumption and the CYP1A2*1F genotype has been shown to impact the age at which breast cancer is diagnosed and the status of estrogen receptors." (PMID 38433141, 2024). "Similarly, coffee consumption combined with CYP1A2*1F genotype was demonstrated to modify age at breast cancer diagnosis and estrogen receptor status." (PMID 28418906, 2017). "However, more in-depth studies are still needed to perform in different ethnicities in order to validate the associations between genetic polymorphisms in the CYP1A2 and CYP3A4 genes and breast cancer to reveal underlying molecular mechanism." (PMID 28418906, 2017). "Additionally, in the present study, there was lack of significant associations between protein expression of CYP1A2 and CYP3A4 in breast cancer tissues and OS." (PMID 28418906, 2017). "The data suggested that CYP1A2 rs2470890 might serve as a novel genetic indicator to evaluate breast cancer prognosis and guide clinical therapy." (PMID 28418906, 2017). "However, to date, lack of studies involving the effect of single nucleotide polymorphisms (SNPs) in the CYP1A2 and CYP3A4 genes on the prognosis and survival of patients with breast cancer." (PMID 28418906, 2017).